CTLA4 (cytotoxic T-lymphocyte associated protein 4)
Diseases named in the same sentence as CTLA4 in open-access papers (continued):
Sharing a sentence is not in itself a finding about the gene and the disease.
tumor (continued). "Interestingly, CTLA4 expression was stable across healthy and tumor tissue, and in the different locations of tumor biopsies, which might be a point of strength for its potential as a therapeutic target for immunotherapy." (PMID 38044986, 2023). "Therefore, inflammation mediated by IL-6–Th17 pathway can probably drive the progress of irEC, so that addition of IL-6 blockers to tumor-bearing mice treated with anti–CTLA-4 reduces Th17, macrophages counts and tumor load, but promotes tumor shrinkage and increases survival rate of mice." (PMID 37404814, 2023). "In KIRC, CD8+ T cells activated by anti-CTLA4 immunotherapy could kill tumor cells." (PMID 36968596, 2023). "Combining the OVT with CTLA-4 blockade could complement the effects of poor tumor targeting through the selective replication ability of OVs in tumor cells and thus dramatically boost anti-tumor therapeutic efficacy." (PMID 36766849, 2023). "Our interaction analysis suggests that myeloid cells might suppress the anti-tumor response by engaging CTLA-4 on CD8+ reactive T cells and additionally secrete a variety of chemokines, which possibly aid in the stimulation and recruitment of malignant T cells." (PMID 36761972, 2023). "Therefore, the roles that PD-1 and CTLA-4 play in the regulation of immune function by Rh2 may also be the key factors against tumor progression." (PMID 37764996, 2023). "A high tumor mutation burden (TMB) consistently correlated with a higher incidence of durable clinical response (DCR) and improved survival after treatment with anti-CTLA-4 or anti-PD-L1 ICIs for cancers which are known to harbor a higher level of somatic mutations." (PMID 37377970, 2023). "Interestingly, anti-CTLA4 combined with anti-PD-L1 could suppress tumor growth and increase survival in a TNBC model." (PMID 37838657, 2023). "These patients may have a defect in earlier steps in the cancer immunity cycle, and combinational immunotherapy including anti-OX40, anti-CTLA4, or anti-angiogenic with PD-1/L1 inhibition may be required to promote tumor immune cell infiltration and improve prognosis." (PMID 36385236, 2023). "Treatment with anti-PDL1 and anti-CTLA4 in combination with mFOLFOX6 chemotherapy for patients with treatment-naive microsatellite stable metastatic colorectal cancer is safe, shows encouraging progression-free survival and induces a tumor-specific immune response." (PMID 37563240, 2023). "Additionally, we performed correlation analysis to corroborate the relationship between tumor infiltrated immune cells and the expression of the seven key hub genes (CTLA4, PRF1, LCK, CD3E, CD247, ZAP70, and LCP2) in ARID1A-PIK3CA mutational co-occurrence tumors." (PMID 38017109, 2023). "These cells may induce immunotolerance through the expression of immune-checkpoint proteins, such as PD-1 and CTLA-4, on the surfaces of cells, interfering with the immune response at the tumor site, in addition to the secretion of immunomodulators, such as interleukin 10, interleukin 35, and TGF-β." (PMID 37111629, 2023). "CTLA-4 is an inhibitory co-receptor constitutively present on Tregs, which plays an important role in regulating CD4+ T cell function, and in HCC, as in other cancer types, it inhibits T cell proliferation through the recognition and differentiation of tumor-associated antigens." (PMID 36769116, 2023). "Similarly, CTLA-4 tail fusion has superior anti-tumor efficacy in a relapsed leukemia model." (PMID 37457699, 2023). "On the one side, the Treg-depleting activity of anti-CTLA4 antibodies described in mouse models has not been replicated in human cancers and subsequent attempts of targeting tumor infiltrating Tregs by an anti-CCR4 antibody were limited by concomitant depletion of effector CD4+ and CD8+ T cells." (PMID 35874810, 2022). "Thus, CTLA-4 blockade through the recruitment of CD8+ cells within the tumor may promote better response as compared to the effect on regulatory T cells." (PMID 35339889, 2022).
tumor (continued). "The LC4 peptide was modified to improve its tumour-targeting ability and reduce peripheral immune system activation, which was obtained through phage display peptide library screening and could block the CTLA-4/CD80 interaction." (PMID 36195696, 2022). "However, it should be noted that a high production of SCFAs, particularly propionate and butyrate (produced by Ruminococcaceae members among others), appeared to limit the antitumor activity of anti-CTLA-4, with reduced systemic inflammation and immune activation in tumor-bearing mice." (PMID 36672796, 2022). "In recent years, the tumor microenvironment (TME) and relevant immune checkpoint inhibitors (ICIs), which target programmed cell death protein 1 (PD-1) and its ligands (PD-L1) and the cytotoxic T-lymphocyte-associated antigen 4 (CTLA-4), have gradually become a focus of research in cancer treatment." (PMID 36741702, 2022). "In addition to the combination therapy with other therapeutic modalities, the combination of CTLA-4 and PD-1 blockers has been suggested to have a synergistic impact on eliciting the anti-tumor activities and consequently lessening the response rates in cancer patients." (PMID 35392976, 2022). "Similarly, gene sets of checkpoint molecules and TIL (tumor-infiltrating lymphocytes) are also enriched in high-risk groups, which indicate effector T-cell deactivation under a higher expression of immune checkpoints like PD-1, TIM-3, and CTLA-4." (PMID 35646664, 2022). "In this study, we demonstrated the negative association of tumor fibrosis with CTLA4 in ccRCC." (PMID 35710350, 2022). "Furthermore, in two other distinct syngeneic tumor models, blunted anti-tumor immunity was observed when FcγR-null animals were treated with either anti-CTLA-4 mIgG2b (clone 9D9) alone or in combination with an irradiated B16-BL6 tumor cell-based vaccine that secretes GM-CSF (GVAX)." (PMID 35237846, 2022). "Moreover, in an in vitro model of TNBC, dual treatment with Alpelisib/Ribociclib evoked an increased tumor immunogenicity due to overexpression of both HLA antigens and CTLA-4 on tumor cell-surface and decreased expression of PD-L1, which is known to be regulated by the PI3K pathway." (PMID 35712501, 2022). "Our findings showed that the high expression of RRM2 in HCC was closely related to PD1, PD-L1, and CTLA-4, suggesting that tumor immune escape may be involved in RRM2-mediated hepatocarcinogenesis, and RRM2 may be a synergistic therapeutic target related to immunotherapy in HCC." (PMID 35911380, 2022). "Therefore, targeting CTLA-4 allows enhancing T cell-mediated anti-tumor activity." (PMID 35330479, 2022). "Moreover, combining regional injection of FeNPs and systemic injection of CTLA-4 antibody could induce a systemic immune response to suppress tumor metastasis and strong immunological memory to avoid tumor recurrence." (PMID 35748543, 2022). "CTLA-4 blockade was shown to inhibit tumor progression by upregulating effector T-cell activity and suppress regulatory T cells (Tregs), which suggest that the patients with high-risk score of the 7-gene prognostic signature might benefit less from CTLA-4 blockade therapy." (PMID 35464857, 2022). "In addition to inhibitory checkpoints such as PD-1 and cytotoxic T-lymphocyte-associated protein 4 (CTLA 4), key cellular mediators of tumor immune tolerance are myeloid-derived suppressor cells, regulatory T-cells, tumor-associated macrophages, and defective antigen-presenting cells." (PMID 35836204, 2022). "For example, Ganetespib induced type I interferon response genes, such as interferon-induced protein with tetratricopeptide repeats (IFIT), through an unknown mechanism and promoted tumor cell killing by autologous T cells in vitro and anti-CTLA4 immunotherapy in mouse model of colorectal cancer." (PMID 36341371, 2022).
tumor (continued). "Therefore, we further compared the expression of immune checkpoint genes in tumor tissues of the high SIRGs score group and the low SIRGs score group and found that PD-L1, CTLA-4, HAVCR2, LAG3, TIGIT and PDCD1 were also up-regulated in the high SIRGs score group." (PMID 36052090, 2022). "We therefore tested whether ALPN-202-mediated anti-tumor activity would be improved when combined with depleting or non-depleting variants of anti-CTLA-4 in the MC38/hPD-L1 model." (PMID 35379805, 2022). "Having established that LEM can target PD-L1 in tumor cells and promote an immunotherapeutic effect in vivo, we next asked whether this strategy may potentiate immunotherapeutic effects in the context of anti–CTLA-4 therapy." (PMID 35239514, 2022). "CTLA-4, which is downregulated in the low-immune group, is the first negative regulator of T cell activation identified in the context of antitumor immunity, and its blockade using monoclonal antibodies triggers tumor regression with durable antitumor immunity in preclinical models." (PMID 36713509, 2022). "When combined with immune checkpoint blockade therapy (anti-PD-1, anti-PD-L1, and anti-CTLA-4), significant tumor remission was observed, indicating that anti-tumor immunity induced by L. monocytogenes vaccination could be further enhanced with immune checkpoint blockade therapy." (PMID 35757741, 2022). "Consequently, in our opinion, an enhancement of mitochondrial function could be a promising strategy for tumor immunotherapy that could be used in combination with the current checkpoint blockade therapies available, such as anti-PD-L1, PD-1, and CTLA-4." (PMID 36467687, 2022). "The unexpected observation of potent anti-tumor activity mediated by H11-HLE, which is devoid of Fc-effector functions, prompted us to interrogate whether Fc effector functions are required for anti-tumor activity observed for ipilimumab, the only clinically approved anti-human CTLA-4 antibody." (PMID 35237846, 2022). "Other factors contributing to immunotherapy resistance include the scarcity of tumor-infiltrating CD8+ T cells, PD-L1 overexpression, loss/overexpression of PD-1, lack of neoantigens, and upregulation of additional immune checkpoint receptors (i.e., CTLA-4, LAG 3)." (PMID 35893814, 2022). "The exhausted tumour-specific T-cells do not express characteristic pro-inflammatory cytokines such as IL-2, TNFα, and IFNγ, but instead produce the inhibitory receptors such as programmed death 1 (PD-1) and cytotoxic T-lymphocyte associated protein 4 (CTLA4)." (PMID 36140243, 2022). "In a fibrosarcoma mice model, administration of anti-CTLA-4 anti-body caused raised levels of the IFN-inducible enzyme 2′,5′-oligoadenylate synthetase (OAS), a positive regulator of anti-tumor response, in draining lymph nodes concurrent with augmented levels of IFNγ in tumor lysates." (PMID 35392976, 2022). "Thus, the immunity of anti-tumor may decrease by action of 4[CTLA-4] and PD-1; these are immune check points." (PMID 35744922, 2022). "The high ratio of Foxp3+ Tregs to CD4+ effector Tcells in subcutaneous tumours may explain why they are refractory to PD-1 blockade.Conversely, the reduced fraction of Tregs in orthotopic tumours may explain theminimal response to CTLA-4 blockade." (PMID 35930804, 2022). "Therefore, immunotherapy using CTLA-4 antibodies might promote T cell activation to help eliminating tumor cells." (PMID 35311155, 2022). "Some immune checkpoints, such as PD-1 and CTLA-4 may lead to anti-tumor immunity." (PMID 35719378, 2022). "Although clinical data have revealed success of PD‐1/PD‐L1 blockade as monotherapy or in combination with CTLA‐4 or chemotherapy, the combination with radiotherapy could further boost anti‐tumour immunity and enhance clinical outcomes due to the immunostimulatory effects of radiation." (PMID 35466515, 2022).
tumor (continued). "These included key genes associated with cytotoxic anti-tumor T cell responses (GZMA, GZMB, PRF1), co-stimulation of T cells (CD27, CD28, ICOS), and genes associated with other immune processes, including Type I IFN response (TNF, TNFSF10), as well as T cell exhaustion (CTLA4)." (PMID 36698398, 2022). "Finally, pathway analysis revealed that IL-37-signaling mediators, such as STAT3, are crucial partners of PD-1, PD-L1, and CTLA-4 pathways, providing hints for an interfering role of this cytokine in the immune-checkpoint blockade of anti-tumor immune responses." (PMID 36551790, 2022). "Therefore, TERT mutations are closely related to higher TMB value and a unique tumor microenvironment, which may be the reason why TERT mutation becomes a potential biomarker for anti-CTLA4 therapy." (PMID 35903534, 2022). "However, the current approach that overcomes tumor evasion of host immunity also disables the immune tolerance checkpoint, leading to significant irAEs, particularly when used in conjunction with anti–CTLA-4 antibodies." (PMID 35239514, 2022). "The gut potential function of intestinal microbes as an immunemodulator (by increasing the anti-tumor effect and potentially reduce irAEs) is so considerable that some ongoing trials are investigating the possibility of combining them with anti PD-1/PD-L1 and anti-CTLA-4 drugs." (PMID 35774996, 2022). "In addition to the typical expression of CD25, CD4, and FOXP3, Treg cells express a number of chemokine receptors and surface molecules, such as CTLA4, PD-1, and TIGIT, which are linked to anti-tumor immunity and may make them a direct target for ICI therapy." (PMID 35967424, 2022). "Individual markers such as CD274 (PD-L1) (P = 0.04) and CTLA4 (P = 0.01) as well as signatures associated with effector cell types such as activated CD8 T cells (P = 0.05) and NK cells (P = 0.05) were also significantly elevated in responders based upon pretreatment tumor samples." (PMID 36923304, 2022). "Although CTLA4 and PD-1 are both immune checkpoints, they can suppress the activation of T-cells in non-redundant manners, and therefore dual blockade may work synergistically to enhance anti-tumor immune responses." (PMID 36159789, 2022). "Because CTLA-4 has a role in early priming and PD-1 in later local tissue response, sequential administration of different checkpoint blockers which target these separate pathways was hypothesized to synergistically boost the anti-tumor immune response." (PMID 36303101, 2022). "In tumor models that were unresponsive to ICIs combined with anti-PD-1 antibodies or anti-CTLA4 antibodies alone, it was further confirmed that intratumoral injection of an oncolytic bovine poxvirus encoding IL-7 and IL-12 combined with ICI therapy improved anti-tumor activity." (PMID 35833121, 2022). "Therefore, many preclinical studies have been conducted on the synergistic effects between RT and immunotherapy using immune checkpoint inhibitors, which suggest that the anti-tumor effects of RT are further enhanced by the concurrent administration of antibodies to CTLA-4 and PD-128–30." (PMID 35508498, 2022). "Immunosuppression has been discovered to be common in the TME due to the lack of antigens in tumor cells and the lack of immunosuppression produced by immune system suppressive signaling pathways such as PD-1/PD-L1 and cytotoxic T-lymphocyte-associated antigen-4 (CTLA-4)." (PMID 36275664, 2022). "The presence of high clonal neoantigen burden in tumours with low neoantigen intra-tumour heterogeneity was furthermore shown to be associated with longer progression free survival in anti-PD-1 treated NSCLC and also associated with longer overall survival in anti-CTLA4 treated melanoma." (PMID 36476325, 2022). "Therefore, the combination of autophagy induction and a CTLA-4 blockade could have a synergistic anti-tumor effect." (PMID 36295867, 2022). "Similarly, a growth inhibition of CTLA-4-expressing tumor cells was also reported." (PMID 35663987, 2022).
tumor (continued). "Therefore, the basic principle of immune checkpoint inhibition is to use antibodies against PD-1, PD-L1, or CTLA-4 for treatment to reverse the inhibitory effect of immune checkpoints and promote anti-tumor effects by preventing the interaction of these receptors." (PMID 35140720, 2022). "To determine whether checkpoint immunotherapy altered the expression of PNAd on tumor vasculature, we treated I.P. tumor-bearing WT mice with either anti-PD-L1 monotherapy or the combination of anti-CTLA4 and anti-PD1 and analyzed PNAd expression after 14 days of outgrowth." (PMID 36189308, 2022). "Others have proposed that, even though treatment with anti-PD-1/PD-L1 and anti-CTLA-4 antibodies would usually expand anti-tumor CD8 + and CD4 + T cells, such treatment might, upon certain circumstances, increase the population of PD-1 + T regs producing an effect of immunosuppression." (PMID 35922755, 2022). "The evasion of tumor cells from immunorecognition was associated with elevated expression of immune checkpoint molecules such as programmed cell death-1 (PD-1, CD279), its ligand PD-L1 (CD274), cytotoxic T-lymphocyte associated protein-4 (CTLA-4, CD152), or the cell surface molecule B7-H3 (CD276)." (PMID 35628262, 2022). "RON is expressed on myeloid cells and recent studies have shown that the anti-tumor activity of anti-CTLA4 antibodies is enhanced in RON kinase domain knockout mice, suggesting that the inhibition of RON may enhance the activity of anti-CTLA4 treatment in enhancing host anti-tumor immunity." (PMID 36581692, 2022). "Therefore, we hypothesized that the B7x-mediated reduction of CTLA-4 would make tumor-infiltrating Tregs poorer targets for immunotherapy and thus reduce the efficacy of anti-CTLA-4 therapy." (PMID 35523809, 2022). "As we observed that tumor samples with low SMG1 expression were more abundant in exhausted CD8 lymphocytes we decided to evaluate whether the inhibition of NMD could improve the outcome of anti-CTLA-4 and anti-PD-1 (ICB) therapy in 4T1 tumors." (PMID 36443756, 2022). "Besides, the combined inhibition of cytotoxic T-lymphocyte-associated protein 4 (CTLA-4) and VISTA is more efficacious, and could increase CD8/Treg and Tcon/Treg ratios in the tumor microenvironment (TME)." (PMID 36158663, 2022). "In particular, ICIs, which are antibodies against cytotoxic T lymphocyte-associated protein 4 (CTLA-4), programmed cell death 1 (PD-1), or its ligand PD-L1, have been successfully applied clinically for solid tumors, relieving the inhibitory effect of the tumor microenvironment on T cells." (PMID 36238278, 2022). "The information respecting the CTLA-4 activities has led to the theory that hindering its action could ease T cell responses to persist, which has implications for progressing an understanding of tumor immunology around that time." (PMID 35392976, 2022). "However, when exposed to tumor antigens for a long time, the expression of tumor suppressors such as PD-1, CTLA4, TIGIT, TRIM3, and LAG3 in the microenvironment will be significantly upregulated, which will lead to impaired killing function and exhaustion of CD8+ T cells." (PMID 36422531, 2022). "Therefore, strategies that ‘boost’ T cell priming, or activation may promote enhanced T cell-mediated anti-tumor responses and improve responsiveness to anti-PD-1 or anti-CTLA-4 ICB8,9." (PMID 36302761, 2022). "Intratumoral injections of CTLA-4 inhibitors have been clinically effective to date, with demonstrated efficacy and safety in phase I clinical trials for the treatment of advanced melanoma, and also showed an enhanced systemic anti-tumor immune response induced by local injections." (PMID 36713427, 2022). "Although the expression difference could be detected between the two subtypes, they were always more stably expressed in tumor samples than those in normal samples (the total fold change was 0.88, p = 0.8672), and only CTLA4 showed higher expression in tumor samples (FC = 1.96, p = 7.57 × 10−6)." (PMID 35741849, 2022).